KISS1 (KiSS-1 metastasis suppressor)
Diseases named in the same sentence as KISS1 in open-access papers (continued):
Sharing a sentence is not in itself a finding about the gene and the disease.
endometriosis (continued). "There is also evidence for the important role of kisspeptin 1 (KISS1) and its receptor (KISS1R) in the pathogenesis of endometriosis." (PMID 35408850, 2022). "The interplay between KiSS-1 nuclear translocation, PI3K/AKT signaling, and mitochondrial stress may represent a pivotal axis in endometriosis pathophysiology." (PMID 41567980, 2025). "KiSS-1 immunolocalization in ectopic and eutopic endometrium of patients with endometriosis and endometrial tissues of control patients without endometriosis." (PMID 41567980, 2025). "The difference in the expression of KISS1/KISS1R in ectopically implanted endometrial tissue compared to the endometrium of women with and without endometriosis suggests their potential future use as biomarkers for early diagnosis of endometriosis." (PMID 40429279, 2025). "A decrease in the KISS1 and KISS1R gene expressions and an increase in the MMR-2 and MMR-9 gene expressions in endometriosis heterotopias compared with a normal endometrium correlates with the changes in the synthesis of the corresponding proteins detected by the immunohistochemistry method." (PMID 38255200, 2024). "There is a decrease in KISS1 and KISS1R values at all stages of endometriosis." (PMID 38255200, 2024). "According to the analysis of the unit area of the KISS1 expression in the eutopic endometrium, statistically significant differences were found in the comparison of the control group with stage I (p = 0.008) and stage III (p = 0.03) of extragenital endometriosis." (PMID 38255200, 2024). "We applied the quantitative polymerase chain reaction and the immunofluorescence method to investigate KISS1, its receptor (KISS1R), MMP-2, and MMP-9 in the eutopic and ectopic endometrium in women with and without endometriosis." (PMID 38255200, 2024). "KISS1 and KISS1R expression are present in the ectopic endometrium of patients with extragenital endometriosis, as opposed to the control group where these proteins were not expressed." (PMID 38255200, 2024). "They demonstrated that KISS1 and KISS1R levels are downregulated in eutopic endometrial stroma from women with endometriosis versus those without the disease." (PMID 35408850, 2022).
breast tumor (7 papers, 2011 to 2025). "For instance, KISS1 expression was shown to be elevated in metastatic breast tumours in several studies, while another showed the opposite." (PMID 35955878, 2022). "This study also demonstrated that KISS1/KISS1R signaling occurs in an autocrine manner in breast epithelial cells to promote in breast tumor development in an animal model." (PMID 30123188, 2018). "Increased KISS1 mRNA and protein in primary breast tumors and lymph node metastasis." (PMID 30123188, 2018). "Recent studies have shown that the expression of KISS1 and GPR54 correlates with breast tumor progression and poor patient prognosis." (PMID 21738726, 2011). "Breast tumors are divided into estrogen receptor α (ERα)-positive and ERα-negative tumors and the role of KiSS-1 and KiSS-1R in the positive group are conflicting." (PMID 29760678, 2018). "In contrast, Jarzabek and colleagues demonstrated that ERα-positive breast tumors express higher levels of both KiSS-1 and KiSS-1R than ERα-negative tumors." (PMID 29760678, 2018). "Increased KISS1 mRNA with the grade of the breast tumors; ERα-positive breast tumors; expressed sevenfold less KISS1 than ERα-negative breast tumors." (PMID 30123188, 2018). "This study also revealed that breast tumors that were positive for lymph node metastasis showed higher KISS1 levels compared to the lymph node negative tumors." (PMID 30123188, 2018). "However, recent studies have demonstrated that an increase in KISS1 and GPR54 expression in human breast tumors correlates with higher tumor grade and metastatic potential." (PMID 21738726, 2011). "So far, it is not possible to assign a clear role to KiSS-1/KiSS-1R system in regulating the progression of ERα-positive and ERα-negative breast tumors as the complex cross-talk between KiSS-1 expression and signaling pathways regulated by ERα deserve further investigation." (PMID 29760678, 2018).
hypogonadism (5 papers, 2013 to 2026). A disorder characterized by decreased function of the gonads. "Earlier data came from studies regarding hypogonadism associated with Kiss1 or Gpr54 knockout mice." (PMID 29593567, 2018). "Disrupting porcine KISS1 is hypothesized to delay or abolish puberty by inducing variable hypogonadotropism and thus preventing the need for castration." (PMID 36685939, 2022). "In contrast, four KISS1-edited pigs (two boars and two gilts) with disruptive allele frequencies of 96% and 100% demonstrated full hypogonadotropism, infantile reproductive tracts, and failed to reach sexual maturity." (PMID 36685939, 2022). "This impaired microglia–GnRH neuron interaction disrupts GnRH neuron function and responsiveness to Kiss1 signaling, without changes in the number of Kiss1 neurons, ultimately resulting in hypogonadism through dysfunction of the HPG axis." (PMID 41818388, 2026). "As for KISS1, a recent abstract described a miRNA that directly targets the 3′ UTR of Kiss1 and is increased in obese individuals with hypogonadism, but due to intellectual property reasons has not been disclosed." (PMID 34831343, 2021).
hypothyroidism (5 papers, 2017 to 2025). Abnormally low levels of thyroid hormone. "However, it remains unclear whether hypothyroidism influences uterine responses to sex steroids throughout the reproductive cycle and whether these effects are linked to alterations in the local expression of Kiss1 and Kiss1r." (PMID 39859259, 2025). "There was a reduction in the stained area of Kiss1 (**P<0.01) and Kiss1r (***P < 0.001) in rats with hypothyroidism." (PMID 37798396, 2023). "In the present study, we investigated the HPG axis of male rats with hypothyroidism, the testicular expression of the Kiss1/Kiss1r system, and the therapeutic potential of Kp10 in the gonadal dysfunction of these animals." (PMID 37798396, 2023). "Interestingly, hypothyroidism led to a reduction in Kiss1 immunostaining in diestrous rats, primarily in the stroma, and also reduced KISS1R gene expression during proestrus." (PMID 39859259, 2025). "In addition to the macroscopic and histological alterations, hypothyroidism reduced Kiss1 and Kiss1r immunostaining and gene expression in the rat’s testis." (PMID 37798396, 2023). "Kiss1 mRNA expression was decreased in both hypothyroidism and hyperthyroidism." (PMID 28432332, 2017). "However, it is unclear whether hypothyroidism also impacts the uterine expression of the Kiss1/Kiss1r system throughout the estrous/menstrual cycle." (PMID 39859259, 2025). "KISS1 might also exert antiapoptotic effects on the placenta: in hypothyroid pregnant rats, the administration of kisspeptin suppresses the apoptotic effect of hypothyroidism, by blocking the activation of the inflammasome NLRP3 pathway." (PMID 38397936, 2024). "The findings of the present study describe the inhibitory effects of hypothyroidism on the HPG axis of male rats, with inhibition of the testicular Kiss1/Kiss1r pathway and an increase in hypothalamic Pdyn expression." (PMID 37798396, 2023). "Unlike what was observed in the ARC of female rats with hypothyroidism, which showed a reduction in Kiss1 protein and mRNA and Nkb mRNA20." (PMID 37798396, 2023). "We found that neither hypothyroidism nor Kp10 treatment did affected Kiss1 mRNA in the ARC (P > 0.05), and the same was observed for Nkb expression (P > 0.05)." (PMID 37798396, 2023). "To do this, we induced hypothyroidism and hyperthyroidism in juvenile female mice by long-term administration of propylthiouracil (PTU) and T4, respectively, then analyzed the change in the regulatory factors of the HPG axis; GnIH, Kiss1, GnRH, LH, and estradiol (E2)." (PMID 28432332, 2017). "However, there is still no information on whether hypothyroidism can affect the testicular expression of the Kiss1/kiss1r system and whether the treatment with kisspeptin could modulate the expression of this system." (PMID 37798396, 2023).
osteosarcoma (5 papers, 2019 to 2021). A usually aggressive malignant bone-forming mesenchymal neoplasm, predominantly affecting adolescents and young adults. "Kiss1 expression has been previously noted in human osteosarcoma cell lines and adjacent tissues as well as in other cancer cell types." (PMID 30777054, 2019). "Previous study demonstrated that prometastasis genes such as MYC 7, 8 and RAS 9 facilitate osteosarcoma metastasis and metastasis‐resistant genes including nm23 10, p16 11 and KiSS‐1 metastasis‐suppressor 12 inhibited the metastasis process in osteosarcoma." (PMID 30868060, 2019). "In osteosarcoma, MNX1-AS1 could accelerate osteosarcoma cell proliferation and invasion via downregulating KISS1." (PMID 33685348, 2021).
preeclampsia (5 papers, 2012 to 2025). Preeclampsia is a hypertensive disorder of pregnancy that is characterized by new-onset hypertension with proteinuria presenting after 20 weeks of gestation, and depending on mild or severe forms may initially present with severe headache, visual disturbances, and hyperreflexia. "Our previous studies demonstrated a higher level of KiSS-1 expression in association with a lower level of MMP-9 expression in the trophoblasts of women with preeclampsia compared with term pregnancy controls." (PMID 23145030, 2012). "Functional enrichment analysis of the 447 human-upregulated DEGs, including ADAM12, ERVW-1, KISS1, LGALS13, PAPPA2, PGF, and SIGLEC6, revealed over-representation of genes implicated in preeclampsia and other pregnancy disorders." (PMID 34154587, 2021). "We have previously reported that the expression level of KiSS-1 was higher in trophoblasts from women with preeclampsia as compared to normal controls." (PMID 23145030, 2012). "We have previously reported that in trophoblasts from women with preeclampsia the expression levels of KiSS-1 were higher and those of MMP-9 were lower, as compared to normal controls." (PMID 23145030, 2012). "They found reduced expression of KiSS-1 and increased expression of KiSS1R in preeclampsia compared with control term pregnancy at both the protein and mRNA levels." (PMID 23145030, 2012). "Elevated KISS1 expression has been found in the placenta of women with preeclampsia." (PMID 40502709, 2025). "Here, using quantitative RT-PCR, Western blot analysis and immunohistochemistry, we extend our analysis to demonstrate that elevated KiSS-1 expression occurs only in early-onset preeclampsia (ePE) and not late-onset preeclampsia (lPE)." (PMID 23145030, 2012). "Notably, several HPGs associated with invasive EVTs (ADAM12, PAPPA2, PGF), and pregnancy complications such as preterm birth and preeclampsia (ADAM12, HSD17B1, KISS1, LGALS13, PAPPA2, SIGLEC6, ERVW-1), were found to be upregulated in human compared to rhesus placenta." (PMID 34154587, 2021). "In this report, we compare the expression levels of both KiSS-1 and GPR54 in placental tissues between preeclampsia and normal pregnancy and determine whether an upregulated expression of either or both genes correlates with early or late-onset preeclampsia." (PMID 23145030, 2012).
prostate carcinoma (5 papers, 2016 to 2026). A carcinoma that arises from epithelial cells of the prostate gland. "Clinically, KISS1 loss is highly observed in metastatic and primary prostate cancer as compared to localized ones." (PMID 39941895, 2025). "Previous research has revealed that KISS1 can not only trigger the proliferation of prostate cancer but also contribute to the metastasis by augmenting the migration, invasion, and angiogenesis of malignant cells." (PMID 41399389, 2026). "SLUG suppresses the KISS1 (metastasis suppressor gene) and enhances the metastasis of prostate cancer." (PMID 39941895, 2025). "KISS1 expression restoration in metastatic prostate cancer cell lines reduces cell invasion motility." (PMID 39941895, 2025). "Our observed increases in KISS1R expression in both LNCaP and 22Rv1 cells after Rb-loss and hypoxia were surprising as a previous report suggested that KISS1 inhibits metastasis and that both KISS1 and KISS1R protein levels appear to decrease with prostate cancer progression." (PMID 27015368, 2016).
hepatocellular carcinoma (4 papers, 2009 to 2026). A malignant tumor that arises from hepatocytes. "Surprisingly, according to the databases in the HPA database, except for breast duct carcinoma (CAB017775), no KISS1 protein was detected in cancers like colon adenocarcinoma (HPA035542), hepatocellular carcinoma (HPA035542), lung adenocarcinoma (HPA035542), and prostate adenocarcinoma (HPA035542)." (PMID 41523580, 2026).
hyperprolactinemia (4 papers, 2016 to 2024). Abnormally high level of prolactin in the blood. "The reduction in Kiss1 during amenorrhea is suggested to be linked to the occurring in the physical lactation state of hyperprolactinemia." (PMID 35163554, 2022). "Therefore, the reduction of Kiss1 gene expression is now believed to be the primary cause of the suppression of gonadotropin secretion during hyperprolactinemia." (PMID 27901187, 2016). "Hyperprolactinemia induces the suppression of hypothalamic Kiss1 neurons that directly control the pulsatile release of GnRH." (PMID 35163554, 2022). "Hyperprolactinaemia induces the suppression of Kiss1 mRNA expression and kisspeptin secretion, leading to a lower stimulation of GnRH neurons, the inhibition of GnRH secretion, diminished GnRH receptor response, and a decline in luteinising hormone pulse frequency and amplitude." (PMID 39407928, 2024).
metastatic disease (4 papers, 2014 to 2023). "In human head and neck squamous cell carcinoma (HNSCC) tumors, loss of KiSS-1 expression has been associated with high metastatic potential compared with non-metastatic tumors." (PMID 29760678, 2018). "Another study, involving the MSG KISS1, revealed a strong correlation between KISS1 immunoreactivity and lower risk of metastatic disease in UM and a better survival rate." (PMID 24688598, 2014).
overnutrition (4 papers, 2018 to 2024). An imbalanced nutritional status resulting from excessive intake of nutrients. "Early-onset overnutrition accelerates these changes, enhances Kiss1 expression and advances puberty." (PMID 30305620, 2018). "In our previous study, we observed that prepubertal female rats with overnutrition experienced earlier onset of puberty, characterized by decreased expression of ghrelin and increased expression of GnRH and KISS-1/Kisspeptin in the hypothalamus compared to malnourished rats." (PMID 39687078, 2024). "It has been found that early-onset overnutrition enhances Kiss1 expression and advances puberty, whereas undernutrition raises SIRT1 levels, protracts Kiss1 repression and delays puberty." (PMID 31920956, 2019).
thyroid cancer (4 papers, 2009 to 2023). "A potential role of the KiSS-1 gene product, metastin, and its receptor in modulating the biological behavior of thyroid carcinomas has been suggested." (PMID 29760678, 2018).
bladder tumors (3 papers, 2014 to 2019). "Patients (n = 69) with lower KISS1 expression in bladder tumors showed a significant association with worse overall survival." (PMID 30123188, 2018). "Furthermore, in this study, the authors observed that all bladder tumors developing distant metastases showed a complete loss of KISS1." (PMID 30123188, 2018). "KISS1 hypermethylation has also been reported in numerous cases of bladder tumors, in correlation with increasing tumor staging and grading." (PMID 31336647, 2019). "These patients presented a better prognosis and a longer survival rate than those with tumors in which KISS1 was downregulated by some mechanisms, like promoter hypermethylation (i.e., colorectal and bladder tumors)." (PMID 31336647, 2019). "As observed in CRC, KISS1 was found to be hypermethylated in over 83% of 804 primary bladder tumors." (PMID 30123188, 2018). "KISS1 expression was significantly lower in bladder tumors with vascular invasion compared with normal urothelium." (PMID 30123188, 2018). "KiSS1 expression is markedly decreased in invasive bladder tumors compared with their respective normal urothelium." (PMID 25272010, 2014). "Lower KiSS1 level is correlated with overall survival in bladder tumors." (PMID 25272010, 2014).
colon carcinoma (3 papers, 2018 to 2020). "Also in line with our data, a previous qualitative research revealed the regulation of miR-199b on the sirtuin 1/cAMP responsive element binding protein/kisspeptin (SIRT1/CREB/KISS1) signaling pathway and may thus influencing colon cancer." (PMID 33489876, 2020).
Delayed puberty (3 papers, 2019). Passing the age when puberty normally occurs with no physical or hormonal signs of the onset of puberty. "The role of KNDY in humans is highlighted from the observations that loss-of-function mutations in the genes encoding for kisspeptin (KISS1), kisspeptin receptor (KISS1R), NKB (TAC3), or NKB receptor (TACR3) are associated with delayed puberty and hypogonadism." (PMID 31920956, 2019).
lung carcinoma (3 papers, 2023 to 2026). "In this study, we focused on the metastasis suppressor gene KiSS1, whose function as a modulator of apoptosis in head and neck and lung cancers has already been demonstrated." (PMID 37790750, 2023). "It has been previously shown that expression of KiSS1 could be increased in lung cancer cells using epigenetic agents, and that KiSS1 could have a pro-apoptotic action in combination with cisplatin." (PMID 37790750, 2023).
lymph node metastasis (3 papers, 2009 to 2018). "Decreased KISS1 expression associated with lymph node metastasis and poorer prognosis." (PMID 30123188, 2018). "Decreased KISS1 mRNA expression and KP-54 protein expression - increased depth of invasion and lymph node metastasis." (PMID 30123188, 2018).
metastatic melanoma (3 papers, 2016 to 2021). A melanoma that has spread from its primary site to another anatomic site. "Kisspeptin 1 (KISS1) is also a well-characterized MSP that is frequently lost in metastatic melanoma and can suppress metastasis in these cells." (PMID 33753879, 2021).
non-small cell lung carcinoma (3 papers, 2018 to 2023). A group of at least three distinct histological types of lung cancer, including non-small cell squamous cell carcinoma, adenocarcinoma, and large cell carcinoma. "More recently, another study from our research team showed a peculiar modulation of KiSS1 levels in liquid biopsies of non-small cell lung cancer (NSCLC) patients, supporting the potential use of KiSS1 as a biomarker for this tumor." (PMID 37790750, 2023). "An inverse correlation between KiSS-1 and MMP-9 has been demonstrated also in non-small cell lung cancer (NSCLC) patients." (PMID 29760678, 2018).
ovarian hyperstimulation syndrome (3 papers, 2017 to 2023). A complication of ovulation induction in infertility treatment. "It is also formally possible that Dax1 deletion in other Kiss1-cells contributes to the subtle reproductive phenotype of ovarian hyperstimulation syndrome." (PMID 37248237, 2023). "Furthermore, the DAX1-dependent restraint of Kiss1 transcription in the arcuate essentially couples it to the activity of the neuron, and loss of this restraint results in elevated FSH secretion and an ovarian hyperstimulation syndrome." (PMID 37248237, 2023).